HMOX1 (heme oxygenase 1)
Diseases named in the same sentence as HMOX1 in open-access papers (continued):
Sharing a sentence is not in itself a finding about the gene and the disease.
ischemic stroke (61 papers, 2010 to 2026). A stroke disorder caused by obstruction of blood flow to the brain, due to thrombotic (local blood clot formation) or embolic (due to a blood clot or other material traveling from another site) event. "The HMOX1 is commonly associated with cardiovascular and neurodegenerative diseases including atherosclerosis and ischemic stroke." (PMID 37529171, 2023). "Further analysis revealed that immunoresponsive gene 1 was induced in microglia after ischaemic stroke, and deficiency in immunoresponsive gene 1 resulted in repressed microglial heme oxygenase-1 expression and exacerbated ischaemic brain injury." (PMID 34557667, 2021). "This regulatory axis EHMT2/HMOX1 may have a potential as a useful diagnostic and therapeutic biomarker in ischemic stroke." (PMID 37529171, 2023). "Moreover, the overexpression of HMOX1 is commonly associated with neurodegenerative diseases, including ischemic stroke." (PMID 37533068, 2023). "Initially, to explore the specific effect of HMOX1 on ischemic stroke, we first simulated ischemic stroke in vitro by OGD/R in microglia (BV-2 cells), and then co-cultured BV-2 cells with HT22 hippocampal neurons." (PMID 37529171, 2023). "Intraperitoneal administration of dimethyl itaconate (DMI), another itaconate derivative, upregulates heme oxygenase-1 (HO-1) expression levels in microglia and ameliorates brain injury in ischemic stroke models." (PMID 37730914, 2023). "Last, more comprehensive investigations about the regulation of other genes by EHMT2/HMOX1 in ischemic stroke are required in our future study." (PMID 37529171, 2023). "Hypoxia-specific anti-RAGA peptide (HSAP), heme oxygenase-1 (HO-1) plasmids and deoxycholic acid-conjugated polyimine form self-assembled nanoparticles through charge interaction for the treatment of ischemic stroke." (PMID 36338131, 2022). "Mechanistic studies revealed that ischaemic stroke-induced IRG1 expression in MG that subsequently promoted microglial heme oxygenase-1 (HO-1) expression to restrain ischaemic brain injury." (PMID 34557667, 2021). "In summary, we demonstrate for the first time that the induction of immunoresponsive gene 1 in microglia following ischaemic stroke serves as an endogenous protective mechanism to restrain brain injury through heme oxygenase-1 up-regulation." (PMID 34557667, 2021). "A key enzyme catalyzing heme oxidative degradation and maintaining redox homeostasis in the cell, heme oxygenase-1 (HO-1), was upregulated by progesterone and vitamin D hormone during treatment of ischemic strokes." (PMID 32399020, 2020). "In the context of ischemic stroke, CO exerts its protective role through the upregulation of Nrf2, a transcription factor that binds to response elements in the promoter region of the heme oxygenase-1 (HO-1) gene." (PMID 40301101, 2025). "The relationship between heme oxygenase‐1 (HO‐1) and human ischemic stroke outcome remains unclear, which was investigated in this study." (PMID 38544366, 2024). "For instance, Andro could increase the expression of nuclear factor erythroid 2-related factor 2 (Nrf2)/heme oxygenase 1 (HO-1) in rats with middle cerebral artery occlusion (MCAO)-induced ischemic stroke, which upregulated p38 MAPK signaling." (PMID 37239873, 2023). "Afterward, we hypothesized that EHMT2 might affect HMOX1 expression by modulating H3K4Me3 level, thereby participating in the occurrence and development of ischemic stroke." (PMID 37529171, 2023). "In addition, polydatin upregulated the endogenous antioxidant nuclear factor erythroid 2-related factor 2, heme oxygenase-1, the thioredoxin pathway, and eventually reversed ischemic-stroke-induced elevation of ROS and inflammation in ischemic cortical tissue." (PMID 31293416, 2019). "It has been reported that heme oxygenase-1 (HO-1) has the most antioxidant-responsive elements (AREs) on its promoter, making it a highly effective therapeutic target for preventing brain damage after ischemic stroke." (PMID 31881005, 2019).
ischemic stroke (continued). "However, it remains unclear how changes in the secretion of MSC cytokines following the overexpression of heme oxygenase‐1 (HO‐1) impact excessive inflammatory activation in a mouse ischemic stroke model." (PMID 37592866, 2024). "Therefore, we speculated that EHMT2 regulated H3K4Me3 to affect the expression of HMOX1, thereby involving the occurrence and development of ischemic stroke, which might provide a promising therapeutic target for the treatment of ischemic stroke." (PMID 37529171, 2023). "Additionally, the upregulation of HMOX1 in BV cells suggested that HMOX1 may be involved in the occurrence and development of ischemic stroke." (PMID 37529171, 2023). "In this regard, up-regulation of HMOX1 may have a protective effect in ischemic stroke." (PMID 37529171, 2023). "ROC monofactor analysis demonstrated a good performance of HMOX1, STAT3, CYBB, and TLR4 in the diagnosis of ischemic stroke." (PMID 36506580, 2022). "First, our experiments in this work were carried out at cellular level and it requires more elaborate animal or clinical experiments to validate whether HMOX1 and EHMT2 also have the same effects in ischemic stroke in vivo." (PMID 37529171, 2023). "Heme oxygenase-1 (HO-1) has been reported as the most effective antioxidant-response element (ARE) in the human body, indicating that HO-1 might be a promising therapeutic target in ischemic stroke." (PMID 35056059, 2021).
viral infections (58 papers, 2010 to 2025). "The role of HO-1 expression and activity in the susceptibility to a variety of viral infections is well known and the polymorphisms in the GT repeats of the promoter of HMOX1 gene is a main variable." (PMID 32993497, 2020). "Heme oxygenase 1 (HO-1) is an inducible enzyme with anti-inflammatory effects, and has critical roles in host defenses against viral infections." (PMID 38961481, 2024). "Heme oxygenase-1 (HO-1) is an antioxidant defense enzyme that displays significant cytoprotective effects against different viral infections." (PMID 38441979, 2024). "miR-24-3p regulates heme oxygenase-1 (HO-1) expression, an inducible enzyme strongly induced by hemin and various stressors, including viral infection." (PMID 34975824, 2021). "An example of such a novel regulator was NFE2L2, which controls the activity of HMOX1 in the context of viral infection." (PMID 34664389, 2021). "The antiviral effects of heme oxygenase-1 (HO-1), a cytoprotective enzyme that inhibits the inflammatory response and reduces oxidative stress, have been investigated in several viral infections." (PMID 34728736, 2021). "Consistently, IF data also showed that virus infection led to a dose-dependent increase in expression of HMOX1 in photoreceptor cells." (PMID 33691741, 2021). "HMOX1 is further involved in interferon regulation following stimulation of the innate immune receptors TLR3 and TLR4, and has been implicated in various viral infections." (PMID 33163005, 2020). "HMOX-1 not only plays a central role in the process of ferroptosis, but its upregulation has also been demonstrated to confer significant protective effects in various diseases, including cardiovascular diseases, inflammatory conditions, and viral infections." (PMID 40573219, 2025). "Moreover, the expression of heme oxygenase-1 (HO-1) was also significantly increased following virus infection in BI-1-overexpressing cells compared to control cells." (PMID 29498634, 2018). "Furthermore, analysis identified that the distribution of these immune cells correlated with the expression levels of IL1-β and HMOX1, suggesting that viral infection in the septic pathological state disrupts the balance between immune activation and suppression." (PMID 40370730, 2025). "Heme oxygenase-1 (HO-1) is an effective cytoprotective enzyme with antioxidant and anti-inflammatory properties and can regulate type I IFN production during viral infections." (PMID 38499512, 2024). "Moreover, under conditions of viral infection, such as HSV-1 or VSV, we also found that knocking out HMOX1 in macrophages increased IFN-I production." (PMID 39621310, 2024). "The inducible cytoprotective enzyme heme oxygenase-1 (HO-1) has gained significant recognition in recent years for mediating strong cellular resistance to a broad range of viral infections, regardless of the type of viruses, viral strains, or mutants." (PMID 35453347, 2022). "Heme oxygenase-1 (HO-1), a key cytoprotective, antioxidant, and anti-inflammatory molecule, was reported to be involved in the activation of IRF3 after TLR3 or TLR4 stimulation, or viral infection." (PMID 20981241, 2010).
osteoarthritis (57 papers, 2013 to 2026). A noninflammatory degenerative joint disease occurring chiefly in older persons, characterized by degeneration of the articular cartilage, hypertrophy of bone at the margins and changes in the synovial membrane. "Recent reports demonstrate that the induction of heme oxygenase-1 (HO-1) enzyme produces analgesic effects in animals with osteoarthritis pain and reverses the grip strength loss caused by sciatic nerve crush." (PMID 37891874, 2023). "The expression of HMOX1 is reduced in humans and mice with osteoarthritis, aggravating cartilage damage and bone remodeling." (PMID 37491214, 2023). "Oxidative stress-mediated activation of the Nod-like receptor protein 3 (NLRP3) inflammasome was also associated with increased expression of NRF2, HMOX1, and IL1B in humans with osteoarthritis." (PMID 34744798, 2021). "What’s more, the chemical component can ameliorate murine osteoarthritis via inhibition of the AKT phosphorylation, nuclear transfer of NF-κB and activation of nuclear factor 2 (Nrf2)/heme oxygenase-1 in an osteoarthritis model." (PMID 34059098, 2021). "We showed that the expression of the activated form of CaMKII, phospho-CaMKII, was increased in human and murine osteoarthritis and the expression of HMOX1 was accordingly reduced, demonstrating the activation of the pathway during disease progression." (PMID 33707504, 2021). "Additionally, naringenin upregulated the antioxidant genes nuclear factor erythroid 2-related factor 2 and heme oxygenase 1, and alleviated OS-induced osteoarthritis." (PMID 39474612, 2024). "Moreover, polyphenol-mediated induction of Hsp32 (heme oxygenase-1) resulted in dramatic improvements in the prognosis of osteoarthritis symptoms in the human population." (PMID 32358783, 2020).
pulmonary fibrosis (55 papers, 2015 to 2026). Chronic progressive interstitial lung disorder characterized by the replacement of the lung tissue by connective tissue, leading to progressive dyspnea, respiratory failure, or right heart failure. "We speculate that there is probably a way of inducing the expression of heme oxygenase 1, with which tissue oxidative stress and inflammation can be inhibited, thus inhibiting pulmonary fibrosis caused by oxidative damage and inflammation of lung." (PMID 36355019, 2022). "We have shown that heme oxygenase-1 (HO-1), an antioxidant, was increased in fibrotic lungs in a bleomycin-induced murine model of lung fibrosis." (PMID 38529321, 2024). "Celastrol also enhanced the antioxidant defense system and provided protection against bleomycin-induced pulmonary fibrosis in rats by inhibiting antioxidant enzymes such as heme oxygenase-1 (HO-1), glutathione S-transferase, and NADPH: quinine oxidoreductase restored via the Nrf2 pathway." (PMID 36978994, 2023).
type 2 diabetes (54 papers, 2009 to 2025). "In a meta-analysis, HMOX-1 gene promotor polymorphisms were found to be associated with the susceptibility to type 2 diabetes." (PMID 37371887, 2023). "Additionally, a long repeat polymorphism in the promoter of the gene encoding HO1, HMOX1 (NCBI Gene ID:3162) associates with worse outcomes in several diseases including coronary artery disease in people with type 2 diabetes." (PMID 29161307, 2017). "Some studies reported increased circulating levels of plasma HMOX1 and gene expression of HMOX1 in circulating monocytes in type 2 diabetes, with reduction in some individuals after metabolic normalisation." (PMID 22474579, 2012). "Our previous study has recently shown that plasma heme oxygenase-1 (HO-1), a stress-responsive protein, is elevated in individuals with type 2 diabetes." (PMID 22427825, 2012). "Similarly, okra polysaccharides have been found to enhance the expression of superoxide dismutase (SOD) and heme oxygenase 1 (HO1) through Nrf2 upregulation, thus exerting a therapeutic effect on type 2 diabetes." (PMID 38671942, 2024). "Long-term L-4F treatment has also been previously reported to have beneficial cardiac functional effects in a genetic type II diabetes mouse model, which were attributed to decreased systemic pro-inflammatory cytokines and increased myocardial expression of heme oxygenase-1." (PMID 32429244, 2020). "However, other studies have reported reduced levels of HMOX1 in muscle and leukocytes at a late stage of type 2 diabetes patients." (PMID 22474579, 2012). "The three most negative beta values derive from type 2 diabetes medication, for transcripts CSF1R, HMOX1, and NEK1 (p < 3.43 × 10−5)." (PMID 36771351, 2023).
anemia (52 papers, 2011 to 2025). A reduction in the number of red blood cells, the amount of hemoglobin, and/or the volume of packed red blood cells. "Consistent with HMOX1‐deficient patients, HMOX1‐deficient rodents displayed reduced body weight, anaemia, chronic inflammation and dysfunction of multiple organs." (PMID 38509740, 2024). "Studies also suggest that selenium is linked to anemia through the modulation of inflammation via the IL-6 pathway, the increased expression of heme-oxygenase 1 and oxidative stress." (PMID 31597392, 2019). "Null mutation of Hmox1 results in significant embryonic mortality as well as anemia and defective iron recycling." (PMID 22162689, 2011). "Notably, HMOX1 deficiency can be fatal, and this is evidenced by HO-1-deficient mice studies, which showed increased vulnerability to anemia, iron deposition, and oxidative stress-induced liver damage." (PMID 41333220, 2025). "The authors consider anemia as one of the risk factors for acquiring symptomatic melioidosis, and iron storage and heme oxygenase-1 (HO-1) activity may play critical roles in the pathogenesis of melioidosis." (PMID 37089599, 2023). "HO-1 is generally considered a fundamental survival enzyme; only two cases of HMOX1 gene deficiency were found in humans, showing phenotypes featuring chronic inflammation, asplenia, anemia, nephropathy, growth retardation, vascular injury, and tissue iron accumulation." (PMID 33923744, 2021). "Hmox1−/− mice are characterized by a very high perinatal lethality and a very severe form of anemia due to low levels of serum iron." (PMID 37513886, 2023). "Exacerbated hemolysis in Hmox1−/− mice resulted in the deterioration of RBC status in 3 day old neonates at the borderline of anemia." (PMID 33092142, 2020). "HMOX1 knockout mice have anemia and iron accumulation in liver and kidney, which is associated with oxidative damage and tissue injury." (PMID 33117818, 2020). "HO-1 knockout mice (Hmox1-/-) show evidence of hepatic and renal iron deposition, serum anemia, and increased vulnerability to oxidative stress." (PMID 33228260, 2020). "An example of human HMOX1 deficiency was found in a 6-year-old boy suffering from growth retardation, anemia, leukocytosis, thrombocytosis, coagulation abnormalities, and hyperlipidemia, indicating an important role of HMOX1 in human health." (PMID 33117818, 2020). "In HO-1-knockout (Hmox1−/−) mice, growth retardation, anemia, iron deposition, and vulnerability to stressful injury were observed." (PMID 31344980, 2019). "HO-1 knockout (Hmox1−/−) mice exhibit growth retardation, anemia, proteinuria, hepatic and renal iron accumulation, chronic inflammation, and reduced life span, which are similar to the important alterations observed in human HO-1 deficiency." (PMID 29599896, 2018). "Hmox1 KO mice showed low serum iron and anemia while they had mild iron loading in liver and kidney at 50 weeks of age." (PMID 23675470, 2013). "Both disease and anemia harm are protected against by inducing Hmox1 and its metabolites." (PMID 38384571, 2024). "In addition, knockout mice with the Hmox1−/− genotype revealed hepatic and renal iron deposition, anemia and increased vulnerability to oxidative stress." (PMID 22518295, 2012). "Besides, several targets such as CA2, HMOX1, GSTA1, and NOS2 were closely associated with anemia, which could exhibit significant influences on the therapeutic effects of XSHG." (PMID 29551975, 2018). "To better understand the tissue (kidney and spleen) iron overload and presence of anemia in mice fed 1.65% Pi diet despite increased EPO secretion, we assessed the expression of heme oxygenase-1 (Hmox-1), an essential enzyme for iron recycling." (PMID 39666728, 2024). "After adjusting for age and presence/absence of anaemia the SNPs GCLC RS10948751 and HMOX1 RS17885925 were also significantly associated with the levels of AOPP (p = 0.030 and p = 0.027, respectively)." (PMID 24693973, 2014).